ITIH5 (inter-alpha-trypsin inhibitor heavy chain 5)
Diseases named in the same sentence as ITIH5 in open-access papers (continued):
Sharing a sentence is not in itself a finding about the gene and the disease.
allergic contact dermatitis (2 papers, 2019 to 2021). An inflammatory skin condition caused by an immune response to direct contact between the skin and an allergen. "Recently, Huth and colleagues confirmed stabilization of HA-cable-like structures by ITIH5 in the skin, while ITIH5 dysregulation was associated with diverse pathological processes including inflammatory diseases such as allergic contact dermatitis." (PMID 33924987, 2021). "ITIH5 is over-expressed in inflammatory skin diseases such as psoriasis, atopic dermatitis and allergic contact dermatitis and specifically in the suprabasal layers of the epidermis." (PMID 30678366, 2019).
benign breast disease (2 papers, 2013 to 2019). "Since plasma shows lower cfDNA concentrations compared to serum, we tested the methylation frequency of SPAG6, PER1, NKX2-6 and ITIH5 in a plasma cohort, consisting of women with a benign breast disease (n = 14) and invasive breast cancer (n = 111)." (PMID 31741713, 2019).
breast tumors (2 papers, 2013 to 2017). "Two genes, ITIH5 and DKK3, met our defined criteria, and were highly specifically unmethylated in sera from healthy women and those affected with benign disease, as well as sera from non-breast tumors." (PMID 23320751, 2013).
Hirschsprung disease (2 papers, 2021 to 2025). Hirschsprung disease (HSCR) is a congenital intestinal motility disorder that is characterized by signs of intestinal obstruction due to the presence of an aganglionic segment of variable extent in the terminal part of the colon. "Of these genes, LAMA4, ZEB2, CTNNAL1, ITGA6 and ITIH5 have previously been associated with Hirschsprung’s disease and ZEB2 was shown to genetically interact with SOX10." (PMID 39982575, 2025). "A previous study has reported that a lncRNA MIR31HG-induced ITIH5 activation could inhibit migration and proliferation in Hirschsprung’s disease." (PMID 34446696, 2021).
metastatic disease (2 papers, 2017 to 2020). "ITIH5 loss predicted shorter overall survival of patients with non-metastatic tumors proposing a prominent role of ITIH5 especially in tumors which tend to metastasize early and whose disease management and personalized therapy is still insufficient." (PMID 28231808, 2017). "Of clinical interest, ITIH5 protein expression was shown to predict tumor relapse of the clinical important subgroup of pT1 high-grade patients, of which 30% never displayed recurrence after transurethral resection of the bladder, while a further 30% died due to metastatic disease." (PMID 32046186, 2020).
pancreatic ductal adenocarcinoma (2 papers, 2021). An infiltrating adenocarcinoma that arises from the epithelial cells of the pancreas. "Previously, we identified ITIH5 as a suppressor of pancreatic ductal adenocarcinoma (PDAC) metastasis in experimental models." (PMID 33024269, 2021). "Poorly expressed ITIH5 was also observed in pancreatic ductal adenocarcinoma, while its restoration could also display an inhibitory function in metastasis of PC cells." (PMID 34446696, 2021).
Stroke (2 papers, 2012 to 2019). Sudden impairment of blood flow to a part of the brain due to occlusion or rupture of an artery to the brain. "Positive expression of inflammation-associated stroke vasculomes (BRM, IκB, Foxf1, and ITIH-5), were quantified using immunofluorescent techniques and analyzed with Image J software." (PMID 30739275, 2019). "Inflammation-associated stroke vasculome including Brahma (BRM), IκB (also called NFκB inhibitor), Foxf1, and ITIH-5 stainings were carried out in the peri-infarct area of the cortex and striatum." (PMID 30739275, 2019). "There were significant downregulation of BRM, IκB, Foxf1and ITIH-5 expression in the peri-infarct area of the striatum of stroke-EPC animals compared to stroke-vehicle animals at 7 days post transplantation (Student t-test; p’s < 0.05)." (PMID 30739275, 2019). "There were significant downregulations of BRM, IκB, Foxf1, and ITIH-5 expression in the peri-infarct area of the cortex of stroke-EPC animals compared to stroke-vehicle animals at 7 days post EPC transplantation (Student t-test; p’s < 0.05)." (PMID 30739275, 2019). "Further analysis revealed, a significant upregulation of the inflammation-associated stroke vasculome including BRM, IκB, Foxf1, and ITIH-5 up to 10 folds after OGD relative to ambient conditions (p’s < 0.05)." (PMID 30739275, 2019). "Similarly, positive expression of inflammation-associated stroke vasculomes (BRM, IκB, Foxf1, and ITIH-5), were quantified using immunofluorescent techniques and analyzed with Image J software." (PMID 30739275, 2019). "Based on the present literature, the upregulation of ITIH5 7 days post stroke could account as a mechanism to regulate the exacerbation of the inflammatory response in our model." (PMID 30739275, 2019). "For stroke, Apcdd1, Atp2b2, Axin2, ITIH-5 and Slc1a1 are specifically expressed in brain vasculome." (PMID 23285140, 2012). "The inflammatory genes in the stroke vasculome include Brahma (BRM), IκB (also called NFκB inhibitor), Foxf1, and ITIH-5." (PMID 30739275, 2019).
adenoma (1 paper, 2013). A neoplasm arising from the epithelium. "We confirmed that ELMO1, EMCN, ITIH5, KCNAB1, and SLCO2A1 were downregulated in follicular carcinoma compared to adenoma." (PMID 24099521, 2013).
bladder tumors (1 paper, 2020). "Of clinical significance, ITIH5 hypermethylation of the CG site #10119075 was associated with shorter overall survival in advanced (pT > 2) bladder tumors." (PMID 32046186, 2020).
cholangiocarcinoma (1 paper, 2024). A carcinoma that arises from the intrahepatic biliary tree (intrahepatic cholangiocarcinoma) or from the junction, or adjacent to the junction, of the right and left hepatic ducts (hilar cholangiocarcinoma). "In summary, for the first time, we described an upregulation of ITIH5 expression in cholangiocarcinoma on mRNA and protein levels compared to normal tissue, abundant ITIH5 expression in the tumor still being associated with favorable overall survival." (PMID 39518085, 2024). "Unexpectedly, however, ITIH5 is significantly upregulated in cholangiocarcinoma (CCA), making it a potential liquid biopsy marker for early CCA detection, as recently shown." (PMID 39518085, 2024). "In conclusion, ITIH5 shows low expression in normal bile duct tissue and is significantly upregulated in cholangiocarcinoma, especially in intrahepatic CCA." (PMID 39518085, 2024). "With regard to the prognostic significance of ITIH5 expression in cholangiocarcinoma, we hypothesized that ITIH5 is functionally involved in mechanisms that may inhibit tumor progression in this tumor entity." (PMID 39518085, 2024). "The re-expression of ITIH5 impairs the colony growth of cholangiocarcinoma cell lines." (PMID 39518085, 2024). "In addition, tumor suppressor proteins such as ITIH5 could also become interesting for the cancer therapy of cholangiocarcinoma in the longer term." (PMID 39518085, 2024).
colorectal cancer (1 paper, 2022). A primary or metastatic malignant neoplasm that affects the colon or rectum. "Besides, the shifted splicing pattern of ITIH5 has been introduced to prognosticate the occurrence of colorectal cancers, while the altered spicing of PTPN6 was involved in leukemogenesis." (PMID 34986865, 2022).
heart failure (1 paper, 2023). Inability of the heart to pump blood at an adequate rate to meet tissue metabolic requirements. "In addition, three target genes (ITIH5, NRK, PDE5A) in DCM and RGS4 in heart failure have been reported to be up-regulated, the expression trend of these genes is consistent with our analysis results." (PMID 37268658, 2023).
invasive breast carcinoma (1 paper, 2019). A carcinoma that infiltrates the breast parenchyma. "We initially assessed promoter methylation of SPAG6, PER1, NKX2-6 and ITIH5 in a serum cohort consisting of samples of women with benign disease (n = 34), DCIS (n = 27) and early invasive breast cancer (n = 42)." (PMID 31741713, 2019).
metastatic cancer (1 paper, 2017). A carcinoma which has spread from the original site of growth to another anatomic site. "It is astonishing that expression of a single ECM factor in vitro, i.e. ITIH5, can effect hyper- or hypomethylation of more than 1500 CpG sites in metastatic cancer cells." (PMID 28231808, 2017).
metastatic melanoma (1 paper, 2021). A melanoma that has spread from its primary site to another anatomic site. "To further evaluate the relationship between clinicopathologic variables and ITIH5 expression levels, we then utilized IHC to assess the expression levels of ITIH5 in primary and metastatic melanoma tissues." (PMID 33935281, 2021).
squamous cell carcinoma (1 paper, 2024). A carcinoma arising from squamous epithelial cells. "Furthermore, increased expression of certain genes, such as ITIH5, was associated with enhanced sensitivity to chemotherapy in squamous cell carcinoma lines." (PMID 39104534, 2024).
thyroid tumours (1 paper, 2009). "Furthermore, UHRF1 and ITIH5 have a potential therapeutic/prognostic value for aggressive thyroid tumours." (PMID 19809427, 2009).
tumor (27 papers, 2008 to 2026). "Inter-alpha-trypsin inhibitor-5 (ITIH5), a class II tumor suppressor gene, encodes a protein that is lost during tumor progression in many solid cancers." (PMID 39518085, 2024). "In all of these tumor entities, clinical collectives have shown that ITIH5 is successively lost during tumor progression and that its loss is associated with unfavorable survival." (PMID 39198923, 2024). "Remarkably, abundant ITIH5 expression was associated with favorable survival, indicating that ITIH5 continues to function as a tumor suppressor protein in CCA." (PMID 39518085, 2024). "ITIH5 expression in CCA is still associated with favorable overall survival; therefore, ITIH5 has a potential tumor suppressive effect in CCA." (PMID 39518085, 2024). "In recent years, the functional consequences of the loss of ITIH5 expression have been intensively studied, highlighting its important role as both a tumor and metastasis suppressor gene in various tumor entities." (PMID 35158755, 2022). "In bladder carcinogenesis, we previously demonstrated epigenetic inactivation of ITIH5 associated with advanced tumor stages predicting unfavorable prognosis of patients diagnosed with a papillary (pT1) urothelial high-grade tumor." (PMID 33924987, 2021). "In this independent cohort, a close association of both ECRG4 and ITIH5 with increased tumor size (pTa vs. pT1-4) and age at diagnosis was determined by Fisher’s exact test." (PMID 32046186, 2020). "In fact, we found that lower expression of ITIH5 was statistically associated with larger tumours, as well as with more aggressive cases, such as PDTC (reaching undetectable levels in the two PDTC cell lines)." (PMID 19809427, 2009). "Altogether, the close association between ITIH2 and ITIH5, and their strong correlation with the estrogen receptor status, suggest that these molecules interact in their tumor-suppressive and metastasis-repressive properties." (PMID 18226209, 2008). "We further analyzed the association between ITIH5 expression and the tumor stage." (PMID 39518085, 2024). "In contrast, loss of ITIH5 in Mel-RM cells promoted tumour progression and lung metastasis ex vivo." (PMID 33935281, 2021). "ITIH5 is considered to be associated with extracellular matrix stability and may therefore play a key role in inhibiting tumor progression." (PMID 33493136, 2021). "ITIH5, a putative tumor and metastasis suppressor gene, known to affect epigenetic reprogramming that has been described to affect therapy response in basal-squamous-like BLCAs was shown to be strongly downregulated." (PMID 41387887, 2025). "Another important downregulated gene found in the E6/E7-HPV80 model is ITIH5, an extracellular matrix protein that is suggested to be a tumor suppressor in various cancers." (PMID 40508156, 2025). "In stark contrast to these previous observations, we have now defined CCA as a tumor entity, where ITIH5 expression is strongly upregulated in the tumor tissue compared to normal tissue (which is bile duct tissue in the case of CCA)." (PMID 39518085, 2024). "ITIH5 (inter-alpha-trypsin inhibitor heavy chain 5) is a protein-coding gene previously reported to be involved in extracellular matrix stabilization and the prevention of tumor metastasis." (PMID 38531844, 2024). "A significant upregulation (approx. 65-fold) of ITIH5 mRNA expression was detected in CCA tumor tissue compared to normal bile duct tissues (p < 0.0001 ***)." (PMID 39518085, 2024). "The gene ITIH5, a known class II tumor suppressor gene (C2TSG), encodes a secreted protein of the extracellular matrix mediating tumor suppressive properties." (PMID 39518085, 2024). "We then used these in vitro tumor models to analyze the effects of ITIH5 re-expression on tumor cell behavior." (PMID 39518085, 2024).
tumor (continued). "One possible therapeutic approach is the recently proposed concept of small-molecule tumor mimetics for class II tumor suppressor genes (C2TSGs), which aims to phenotypically mimic the effect of tumor suppressor proteins such as ITIH5." (PMID 39518085, 2024). "ITIH5 was first revealed as a putative tumor suppressor gene in 2008 and various studies confirmed the involvement of ITIH5 in impairing tumor cell growth in vitro." (PMID 35158755, 2022). "In the present study, we aimed to give an insight into the ITIH5-mediated inhibition of tumor cell growth in a mouse model while considering the role of truncated ITIH5 proteins, with a special focus on VIT, independently of the HA-binding function." (PMID 35158755, 2022). "Subsequently, ITIH5 has been characterized as a putative tumor and metastasis suppressor gene in various tumor entities such as breast, bladder, lung, colorectal, and cervical cancer." (PMID 35158755, 2022). "Beginning on Day 6 after tumor cell injection, the transplanted ΔpBK-mock control cells lacking ITIH5 expression grew much faster than the corresponding ΔpBK-ITIH5 cells showing ITIH5 overexpression." (PMID 35158755, 2022). "In the present study a translational approach was pursued to develop truncated polypeptides derived from the full-length ITIH5 protein that are able to mimic its tumor suppressive functions." (PMID 35158755, 2022). "ITIH5 is a typical so-called Class II tumor suppressor gene that is inactivated by promoter DNA methylation rather than by genetic alteration." (PMID 35158755, 2022). "In vitro, we confirmed a tumor suppressive role of ITIH5 in CD44 expressing SCaBER cells reflecting the BASQ subtype but not in basal-type HT1376 cancer cells with lower CD44 (variant) expression." (PMID 33924987, 2021). "Based on the experimental results, we found that upregulation of LINC00261 has tumor suppressive functions in PC stem cells through a regulatory mechanism that LINC00261 increased expression ITIH5 by recruiting GATA6." (PMID 34446696, 2021). "Consistent with previous reports, ITIH5 expression impaired tumor cell and colony growth as well as cell capacities to colonize an artificial wound in vitro." (PMID 33924987, 2021). "ITIH5 overexpression significantly suppressed the growth of SK-Mel-28 xenograft tumours, as indicated by the reduced tumour weights and tumour sizes compared with those of the control group." (PMID 33935281, 2021). "As anticipated, ITIH5 levels were higher in ITIH5- and ITIH5Δs-expressing tumours than in control tumours." (PMID 33024269, 2021). "ITI heavy chain 5 (ITIH5) was revealed to have close correlation with tumor suppression in diverse kinds of cancers." (PMID 34446696, 2021). "In the TMA, IHC for ITIH5 revealed that ITIH5 levels in metastases were similar to those in primary tumours." (PMID 33024269, 2021). "To reveal the potential molecular mechanism by which ITIH5 inhibits the tumour progression of melanoma, we used ITIH5 as bait to search for new ITIH5-interacting partners by mass spectrometry analysis." (PMID 33935281, 2021). "At first, the functional impact of forced overexpression of ITIH5 on tumor colony growth was studied using 2D colony formation assays in vitro." (PMID 28231808, 2017). "Furthermore, in the CCA TMA data, a tendency of higher ITIH5 expression in earlier tumor stages was observed." (PMID 39518085, 2024). "This raises the question of whether ITIH5, although higher expressed, still has a tumor suppressive function, as in all other tumor entities described so far, or whether it may exceptionally act as a cancer-promoting factor in this specific tumor entity." (PMID 39518085, 2024).